UHRF1 (ubiquitin like with PHD and ring finger domains 1)
Diseases named in the same sentence as UHRF1 in open-access papers (continued):
Sharing a sentence is not in itself a finding about the gene and the disease.
breast carcinoma (28 papers, 2014 to 2025). "The past reports have described a significant association between high UHRF1 expression and poor outcome of bladder cancer, breast cancer and pancreatic cancer." (PMID 30352833, 2018). "Like for other cancers, many studies have reported the association of UHRF1 with breast cancer which is one of the leading causes of cancer related deaths in women world-wide, killing around 0.5 million women each year." (PMID 28881702, 2017). "Moreover, UHRF1 has been implicated in regulating the transcription of BRCA1 in sporadic breast cancer." (PMID 39051184, 2024). "Recently, a study has investigated UHRF1 as a diagnostic and prognostic marker for breast cancer." (PMID 28881702, 2017). "Overexpression of UHRF1 has also been described in breast cancer cells, and could be linked to the degree of breast cancer aggression and its pathological stage." (PMID 26884069, 2016). "In breast cancer, Prevotella copri reduces host IPyA levels and thereby promotes tumor growth via UHRF1 mediated phosphorylation of AMP-activated protein kinase (AMPK)." (PMID 41339918, 2025). "UHRF1’s implication in the progression and prognosis of various solid tumors, including osteosarcoma, lung cancer, and breast cancer, has underscored its pathological significance." (PMID 39051184, 2024). "Several studies have defined UHRF1 as an oncogene in various tumours, including breast cancer, cervical squamous cell carcinoma, prostate cancer, and osteosarcoma." (PMID 39046429, 2024). "This review focuses on the functional domains of UHRF1, highlighting its key interacting proteins and oncogenic roles in solid tumors including retinoblastoma, osteosarcoma, lung cancer, and breast cancer." (PMID 39051184, 2024). "This lowering of IPyA levels results in breast cancer progression due to the phosphorylation of AMPK1 via increased transcription of UHRF1." (PMID 39796699, 2024). "Clinical data have shown that UHRF1 is overexpressed and correlates with poor survival in luminal-type breast cancer patients." (PMID 37630248, 2023). "This suggests a novel role of UHRF1 in luminal-type breast cancer, but further studies are needed to investigate the effect of naphthazarin or its derivatives against this cancer." (PMID 37630248, 2023). "A recent study reported that UHRF1 modulates the growth of breast tumor cells through estrogen signaling, and its depletion significantly inhibits breast cancer cell growth in vitro and in vivo." (PMID 37630248, 2023). "For instance, the upregulation of UHRF1 in breast cancer was shown to result in hypermethylation and inhibition of BRCA1 by forming an inhibitory transcriptional complex consisting of HDAC, DNMT1, and G9a over its promotor." (PMID 36077796, 2022). "Aberrant expression of the UHRF1 gene has been found in different types of cancer like breast cancer, gastric cancer, hepatocellular carcinoma, renal cell carcinoma, squamous cell carcinoma, and osteosarcoma." (PMID 31245293, 2019). "A large number of studies have shown that UHRF1 is highly expressed in a variety of malignant tumor tissues, including breast cancer, bladder cancer, and prostate cancer and that it is involved in tumorigenesis and cancer progression." (PMID 31803739, 2019). "Other studies also showed that inhibiting UHRF1 enhances the chemosensitivity in breast cancer and radiosensitivity in esophageal squamous cell carcinoma." (PMID 31064417, 2019). "It has been suggested that the UHRF1 mediated transcriptional repression of MDR1 has the potential to overcome multidrug resistance during the treatment of breast cancer." (PMID 31245293, 2019). "Related studies have also found that UHRF1 is highly expressed in breast cancer, bladder cancer, prostate cancer, and CRC." (PMID 31803739, 2019). "Therefore, the level of UHRF1 DNA in plasma is substantially indicative of the status and stage of breast cancer; and may serve as a useful diagnostic and clinically prognostic marker of breast cancer." (PMID 29899856, 2018).
breast carcinoma (continued). "Elevated levels of UHRF1 DNA in plasma directly correlated with short progression-free survival of breast cancer patients." (PMID 29899856, 2018). "Data derived from cDNA-microarray studies confirmed UHRF1 (ICBP90) overexpression in a variety of primary breast cancer samples." (PMID 29899856, 2018). "Ubiquitin-like with PHD and ring finger domains 1 (UHRF1) has been reported to be overexpressed in various cancers such as breast cancer and lung cancer." (PMID 28160558, 2017). "In 2003, we first reported increased expression of UHRF1 in breast cancer tissues and found a relationship between its expression and pathological grade of cancer." (PMID 28881702, 2017). "The origin of the enhanced UHRF1 expression in breast cancer remains elusive in contrast to the down-stream events." (PMID 28881702, 2017). "Knockdown of UHRF1 expression in cancer cells suppressed cell growth significantly, and the overexpression of UHRF1 promoted the proliferation of breast cancer cell lines by inducing apoptosis inhibition and angiogenesis." (PMID 26859141, 2016). "According to former studies, high expression of UHRF1 was also detected in lung cancer cells, particularly in prostate cancer and breast cancer and it seem that the intensity of its over-expression was linked to the clinical stage of the cancer." (PMID 27431502, 2016). "UHRF1 has been identified as a significant promoter of cell proliferation and tumor growth in numerous cancers, including retinoblastoma, osteosarcoma, lung cancer, and breast cancer." (PMID 39051184, 2024). "Additionally, the avenues for modulating UHRF1’s influence on breast cancer progression extend to its downstream genes." (PMID 39051184, 2024). "In breast cancer, UHRF1 has been identified as a bonafide biomarker." (PMID 29899856, 2018). "Ultimately, breast cancer patients with high UHRF1 expression are likely to have a poor prognosis." (PMID 29899856, 2018). "Indeed, a large percentage of cells, analyzed from low and high grade breast carcinomas, highly express UHRF1, and additionally, UHRF1 expression levels matched the grade of cancer." (PMID 29899856, 2018). "Similarly, it has been observed that specific inhibition of UHRF1, by mRNA targeting, decreased the oncogenic capacity in breast cancer cells and increased their sensitivity to chemotherapy." (PMID 28881702, 2017). "Notably, increased expression of UHRF1 in breast cancers is believed to aggravate the pathogenesis by silencing BRCA1 and modulating the estrogen receptor-α expression." (PMID 28881702, 2017). "Later UHRF1 overexpression in breast cancer patients was reported by cDNA microarray and qRT-PCR." (PMID 28881702, 2017). "UHRF1 overexpression also increased the proliferation and migration potential of breast cancer cells as exogenous expression of UHRF1 in MDA-MB-231 breast cancer cells facilitated their passage through the cell cycle by induction of cyclin D1 and prevention of apoptosis." (PMID 28881702, 2017). "In breast cancer, BRCA1 has been reported as a target of UHRF1-mediated methylation, while in non-small-cell lung cancer, RASSF1, CYGB, and CDH13 have been identified as UHRF1-regulated methylation targets." (PMID 41373864, 2025). "Depletion of UHRF1 also induced global DNA demethylation in a CIMP-negative CRC cell line (SW480) and in a breast cancer cell line (MFC7), suggesting UHRF1 is required to maintain DNA methylation in multiple tumor types." (PMID 31064417, 2019). "Depletion of UHRF1 also enhanced radio sensitivity of highly aggressive, triple negative MDA-MB-231 human breast cancer cells." (PMID 31245293, 2019). "In conclusion, the overexpression of AURKB, GINS2, MCM10, UHRF1, POLE2, SPC24, and E2F2 in HER2-positive breast cancer patients with ALR showed that these hub genes could be potential prognostic biomarkers in such patients." (PMID 33013420, 2020).
breast carcinoma (continued). "UHRF1 depletion led to demethylation in the CpG islands of well-known tumor-related genes in both CIMP-positive and CIMP-negative CRC cell lines, as well as in a breast cancer cell line." (PMID 31064417, 2019). "Furthermore, while knockdown of either UHRF1 or UHRF2 led to increased DNMT3A, a more pronounced increase of DNMT3A was observed when both UHRF1 and UHRF2 were knocked down in the MDA-231 breast cancer cell line, indicating that UHRF1 and UHRF2 cooperatively regulate DNMT3A." (PMID 27462454, 2016).
lung cancer (28 papers, 2010 to 2025). A malignant neoplasm involving the lung. "We next assessed the impact of UHRF1 loss on the in vivo growth of human KRAS-driven lung adenocarcinoma cells using a competitive growth assay in a xenograft model of lung cancer." (PMID 37407562, 2023). "To assess the impact of UHRF1 loss on DNA methylation in KRAS mutant lung cancer cells, we depleted UHRF1 or KRAS using siRNA in two KRAS-driven cell lines (H358 and A549) and analyzed changes in DNA methylation." (PMID 37407562, 2023). "UHRF1 is a novel diagnostic marker of lung cancer, UHRF1 controls the cell cycle by silencing tumor suppressor genes, and the overexpressed UHRF1 was related to the poor survival of NSCLC patients." (PMID 35884544, 2022). "Although UHRF1 overexpression was associated with these malignant indicators, UHRF1 was detectable in half of lung cancer patients in an early pathological stage." (PMID 20517312, 2010). "We further found that overexpression of UHRF1 in Japanese lung cancer cases associated with gender (higher in male) and smoking." (PMID 20517312, 2010). "The expression of UHRF1 was associated with poor prognosis and several other clinicopathological characteristics of the lung cancer patients." (PMID 20517312, 2010). "Also, previous studies demonstrated that the expression level of UHRF1 is closely associated with clinical stage, metastatic and prognostic of bladder cancer and lung cancer." (PMID 27431502, 2016). "This alteration in UHRF1 expression could be linked to the degree of the lung cancer aggressiveness and was detectable in half of the patients in an early pathological stage." (PMID 21496237, 2011). "As UHRF1 was specifically expressed in cancer cells and detectable in approximately half of lung cancer cases in an early pathological stage, UHRF1 could be a novel diagnostic marker for lung cancer." (PMID 20517312, 2010). "This suggests therefore that UHRF1 could be a novel diagnostic tool for lung cancer." (PMID 21496237, 2011). "As no large-scale study of UHRF1 expression in lung cancers has been performed, we examined whether UHRF1 could be a novel diagnostic marker of lung cancer by immunohistochemical analysis to understand the clinical importance of this protein in lung carcinogenesis." (PMID 20517312, 2010). "However, we would like to emphasise that overexpressed UHRF1 was detectable in approximately half of lung cancer patients in an early pathological stage by immunohistochemistry, indicating that UHRF1 can be a diagnostic marker of lung cancer even in the early stage." (PMID 20517312, 2010). "UHRF1 overexpression has been found in various sub-types of lung cancer, and can be used for the precision diagnose of lung cancer." (PMID 38725075, 2024). "Recently, UHRF1 was identified as a mediator of KRAS-driven lung cancer, whereby knockout of UHRF1 in KRAS mutant cells leads to reduced tumor growth and promotes apoptosis." (PMID 38914477, 2024). "UHRF1 overexpression has been observed in a panel of cancer types, including lung cancer, breast cancer, gastric cancer, prostate cancer, colorectal cancer, cervical cancer, pancreatic cancer, bladder cancer, endometrial cancer." (PMID 38725075, 2024). "In human lung cancer models UHRF1 knock-out selectively impaired growth and induced apoptosis only in KRAS mutant cells." (PMID 37407562, 2023). "These screens identified Ubiquitin-like with PHD and ring finger domains 1 (Uhrf1) as a gene uniquely essential for the growth of primary lung cancer spheroids." (PMID 37407562, 2023). "In summary, our study reveals that long-term gefitinib/osimertinib exposure enhances genome-wide methylation and promotes drug resistance in lung cancer cells through UHRF1/DNMT1-mediated epigenetic silencing of MUC17." (PMID 36778111, 2023).
lung cancer (continued). "In lung cancer patients with tumors harboring a KRAS mutation, high UHRF1 expression is anticorrelated with tumor suppressor gene expression and predicts poor patient survival." (PMID 37407562, 2023). "To extend these observations and determine if UHRF1 loss affects 3D growth of human NSCLC cells, we used CRISPR/Cas9 to knock-out UHRF1 using two sgRNAs in a panel of human lung cancer cell lines." (PMID 37407562, 2023). "Overexpression of UHRF1 rescued double-strand break repair, and depletion of UHRF1 reduced the chemosensitivity of KRAS mutant lung cancer cells." (PMID 35884544, 2022). "Researchers showed a proapoptotic effect of MIR9-1 in patients with lung cancer and suppression of cell proliferation mediated by ubiquitin-like with PHD and ring finger domains 1 (UHRF1)." (PMID 35740309, 2022). "UHRF1 plays a significant role in skin, liver, prostate, breast, colon, kidney, bladder, and lung cancers, as well as hematological malignancies." (PMID 33658396, 2021). "Of interest, we focused on the role of UHRF1 in lung cancer; however, the UHRF1 expression in lung cancer was inconsistent from different groups." (PMID 32495469, 2020). "UHRF1 overexpression is characteristically observed in many forms of cancer, including lung carcinomas starting from an early pathological stage." (PMID 29899856, 2018). "Immunohistochemistry (IHC) analysis of 322 lung cancer tissues from Japan and 56 samples from US, revealed an overexpression of UHRF1 in all histological types of non-small cell lung cancer (NSCLC) especially in non-adenocarcinomas." (PMID 28881702, 2017). "As enhanced expression significantly correlated with the advanced stages and malignancy of the cancer, authors proposed UHRF1 as a prognostic biomarker for lung cancer." (PMID 28881702, 2017). "Accordingly, in a cell model of lung cancer, knockdown of UHRF1 in A549 cells prevented the tumor suppressor genes RASSF1, CYGB, and CDH13 promoters from hypermethylation." (PMID 28881702, 2017). "Transcript analysis of samples also showed marked increase of UHRF1 mRNA in 70% of lung cancer cases." (PMID 28881702, 2017). "UHRF1 is featured by a SRA domain (Set and Ring Associated) only found in the UHRF family, and up-regulation of UHRF1 has been observed in a variety of cancers, such as lung cancer and bladder cancer." (PMID 27431502, 2016). "Having observed an inverse correlation between UHRF1/2 and DNMT3A proteins in lung cancer specimens, we next examined further the causal role of UHRF1/2 overexpression in downregulation of DNMT3A proteins in multiple lung cancer cell lines." (PMID 27462454, 2016). "Alteration in UHRF1 expression is correlated with the degree of the lung cancer aggressiveness and it was detected in 50 % of the patients in an early clinical stage." (PMID 27431502, 2016). "The qRT–PCR, which is more sensitive than immunohistochemistry, revealed that UHRF1 mRNA level was up-regulated in approximately 70% of the overall lung cancer cases." (PMID 20517312, 2010). "To validate the microarray data, we examined UHRF1 protein expression levels in the 56 US lung cancer cases by immunohistochemistry with information of age, gender, histological type, and pT and pN factors of their cancers." (PMID 20517312, 2010). "In this report, we performed, for the first time, a large-scale analysis of UHRF1 expression in lung cancer cases with clinical information." (PMID 20517312, 2010). "Although overexpression of UHRF1 associated with lung cancer malignancy, approximately half (47%) of Japanese lung cancer patients in T1 stage showed high expression of UHRF1 similarly to the US cases." (PMID 20517312, 2010). "Studies in mice with KRAS-driven lung cancer have shown that depleting UHRF1 slows tumor growth." (PMID 39051184, 2024). "In fact, targeting UHRF1 in combinational immunotherapy of lung cancer has already been undergone." (PMID 38317133, 2024).